FUT8 (fucosyltransferase 8)
Diseases named in the same sentence as FUT8 in open-access papers (continued):
Sharing a sentence is not in itself a finding about the gene and the disease.
cancer (continued). "The feature selection procedure extracted several cancer-related and lymph node metastasis-related genes, such as TP73, PDX1, FUT8, HOXD1, NMT1, and SEMA3E." (PMID 28951630, 2017). "FUT8 is not classified as an essential gene in both sensitive and resistant cancer cell lines, despite marginally higher essentiality scores in TKI-resistant cells than sensitive cells." (PMID 36961502, 2023). "An intestinal immune network for IgA production might provide new markers in enteric DLBCL, such as CCR10, TNFRSF13B, AICDA, and HLA-DOB, as well as genes involved in transcriptional misregulation in cancer (NFKBIZ, FUT8, LMO2, CCND2, BCL2A1, ETV6, and CDK14)." (PMID 29992138, 2018). "Unlike other FUTs, only FUT8 can catalyze α1,6-fucosylation (core fucosylation) that are particularly involved in a variety of physiological processes and in cancer biology." (PMID 29975776, 2018).
tumor (74 papers, 2013 to 2026). "The correlations between FUT8 expression and cellular functions, tumor mutation burden, immune checkpoint genes, and immune infiltration were analyzed." (PMID 40729369, 2025). "In recent years, studies have found that the expression of FUT8 is associated with the occurrence and development of various tumors and can modulate the expression of tumor-related factors." (PMID 40729369, 2025). "Higher FUT8 expression was associated with higher tumor mutation burden and significant correlations with multiple immune checkpoint genes." (PMID 40729369, 2025). "FUT8 expression was significantly associated with tumor purity and the extent of infiltrative immune cells." (PMID 40373023, 2025). "FUT8 is involved in regulating multiple tumor behaviors and is closely associated with malignant transformation." (PMID 38256141, 2024). "According to the findings on EMT in NSCLC, also PMT in GBM has been recently associated with the increase in FUT8 expression and core-fucosylation, in parallel with significantly faster tumor growth and matrix invasion." (PMID 36980181, 2023). "Genomic analysis of HCC patients inspired that overexpressed of FUT8 gene, the cause of core fucosylation, indicated that these glycan changes promoted hepatocarcinogenis, letting them potential tumor biomarkers and therapeutic targets." (PMID 33282554, 2020). "We explored the association between FUT8 expression and tumor purity further." (PMID 40373023, 2025). "It was proved by experiments that knocking down FUT8 could inhibit the proliferation and invasion of tumor cells,suggesting that FUT8 could serve as a diagnostic and prognostic biomarker for LUAD and LUSC and as a therapeutic target for immunotherapy." (PMID 40373023, 2025). "Using amiRNA variants of miR‐34a‐5p, which is a known FUT8 regulator in human tumour cells, we could adjust the stable afucosylation effect of the native miRNA." (PMID 38845814, 2024). "Current reports mainly focus on the functional effects of FUT8, but investigating the underlying causes of aberrant expression and the detailed regulatory mechanisms is of great significance for early tumor diagnosis and the development of new therapeutic targets." (PMID 38256141, 2024). "Except for the direct up‐regulation of PD‐L1 that co‐occurred with HPV‐CD274 integration, as observed above, the up‐regulation of FUT8 caused by viral integration was found to have a positive correlation with PD‐L1 and catalysed its glycosylation, facilitating tumour immune evasion." (PMID 38279874, 2024). "This is consistent with the correlation that upregulation of FUT8 is associated with increased tumor metastasis and worse survival in NSCLC, indicating that FUT8 may also be a potential prognostic biomarker for NSCLC." (PMID 36895477, 2023). "FUT8 is a protein-coding gene that encodes an enzyme belonging to the family of fucosyltransferases involved in many pathological/physiological activities such as tumor metastasis and inflammation), and regulating the fucosylation of O-glycans and N-glycans." (PMID 36849997, 2023). "In human GB FUT8, overexpression is associated with high tumor grade and aggressive disease." (PMID 35682991, 2022). "Although the mechanism underlying alteration of the NF-κB2 signaling pathway following core fucosylation of TNFR should be further studied, our present results show that high expression of FUT8 which result in the suppress of NF-κB2 signaling pathway in OS cells is associated with tumor suppression." (PMID 34857735, 2021). "As expected, a cytotoxic T-lymphocyte assay indicated that knockdown of FUT8 restored the tumor cells’ susceptibility to cytotoxic T-cell-mediated death only in cells with re-expression of glycosylated B7H3 but not in cells with re-expression of non-glycosylated B7H3." (PMID 33976130, 2021). "FUT8 expression level has been linked to tumor clinical features and outcomes in numerous studies." (PMID 33323540, 2020).
tumor (continued). "FUT8 protein levels were significantly higher in Gleason grade 7 and Gleason grade 8–10 (8+) tumours compared to Gleason grade 6 tumours (p < 0.01 and p < 0.0001) and in patients with metastasis compared to patients with localised disease (p = 0.0084)." (PMID 40387385, 2025). "Next, using sub‐cutaneous xenograft models, we found that overexpression of FUT8 increased the growth of CWR22Rv1 tumours by 2.23 fold (p = 0.1993) whereas knockdown of FUT8 significantly suppressed the growth of PC3 tumours (p = 0.0055)." (PMID 40387385, 2025). "Elevated FUT8 expression modulates multiple signaling pathways, potentially impacting cell transformation, proliferation, and contributing to tumor progression." (PMID 40373023, 2025). "FUT8 was significantly overexpressed in CRC tumor tissues and correlated with various cellular functions such as stemness, invasion, EMT, and metastasis." (PMID 40729369, 2025). "The results revealed a significant difference in FUT8 expression between the two cell lines, with tumor cells showing a notably higher level of FUT8 protein compared to normal colon cells." (PMID 40729369, 2025). "FUT8 plays an important role in tumor immunology, mainly by regulating the glycosylation state of the surface glycoprotein of tumor cells to affect the immune escape and immunotherapy effect of tumors." (PMID 40373023, 2025). "Collectively, this study reveals a mechanism underlying CD47 upregulation in tumor cells and highlights the potential of targeting the FUT8-SMURF1-CD47 axis as a therapeutic strategy to improve anti-tumor immune responses." (PMID 41355073, 2025). "In order to investigate the differences in FUT8 protein expression between normal colon cells and tumor cells, NCM460 cells and SW480 cells were selected for culturing in this study." (PMID 40729369, 2025). "Inhibition of core fucose-transferase Fut8 by gene ablation or drug inhibition reduces cell surface expression of PD-1 and enhances T cell activation, resulting in more effective tumor eradication." (PMID 40373023, 2025). "Aberrant FUT8 expression disrupts the function of critical cellular components and triggers the abnormality of tumor signaling pathways, leading to malignant transformations such as proliferation, invasion, metastasis, and immunosuppression." (PMID 38256141, 2024). "We demonstrated that inhibition of fut3 and fut8 using 2F-PerAcFuc directly reduced the production of CD15s and core fucosylation of E-cadherin in the xenograft model of tumor tissue in nude mice." (PMID 38911244, 2024). "In melanoma cells, FUT8 promotes invasion and tumor dissemination, partially due to impaired L1CAM cleavage caused by its aberrant core fucosylation." (PMID 38256141, 2024). "Further investigations are warranted to elucidate the underlying mechanisms through which 2F-PerAcFuc influences FUT3 and FUT8 expression and to assess its broader impact on cellular functions and tumor progression." (PMID 38911244, 2024). "Given the remarkable variation in biological functions and regulatory mechanisms of FUT8 across different tumor types, gaining a comprehensive understanding of its complexity is imperative." (PMID 38256141, 2024). "Through HNSCC tissue microarray analysis, we further confirmed that higher expression of FUT8 in tumor cells (high: positive ratio ≥ 10%; low: positive ratio < 10%) was intimately associated with poorer prognosis." (PMID 38548747, 2024). "During the tumor progression, aberrant expression of FUT8 often coincides with an increase in tumor metastasis, despite the diverse range of specific molecular mechanisms involved." (PMID 38256141, 2024). "Considering that PASMCs have many tumor-like characteristics, such as disordered proliferation and resistance to apoptosis, the present study aimed to explore the role of FUT8-mediated core fucosylation in the pathogenesis of PAH." (PMID 37196106, 2023).
tumor (continued). "The interaction of FUT8 with the proliferation and migration of various tumor cells and its epithelial-mesenchymal transition (EMT) have been studied." (PMID 37196106, 2023). "FUT8 catalyzes the addition of fucose unit to the GlcNAc at the end of N-glycans to form core fucosylation, which promotes tumor invasion and migration by regulating downstream pathways, such as TGF-β, EGFR, and Wnt/β-catenin." (PMID 35752750, 2022). "Fut8-mediated core-fucosylation is an important post-translational modification and is related to tumor progression and immune response, as well as cell growth and differentiation." (PMID 35670884, 2022). "Currently, the research on FUT8 has focused on tumor and intestinal inflammation—mainly in humans and mice—and there are few studies on the relationship between the expression level of the pig FUT8 gene and the drug resistance of Escherichia coli." (PMID 36499043, 2022). "Genetic ablation or pharmacological inhibition of FUT8 reduces cell-surface expression of the immune checkpoint protein PD-1, thus promoting enhanced T cell activation, and resulting in more effective tumour eradication." (PMID 33466384, 2021). "While examining FUT8 protein expression in fresh human TNBC tissues, we observed that out of 14 pairs of samples, 9 pairs (64%) had significantly higher levels of FUT8 protein in tumor tissues than that in matched normal tissues." (PMID 33976130, 2021). "In previous studies, many alterations including the up-regulation of FUT8 39, increased core-fucosylation 40, excessive demands of folate, and the abnormal abundance of FOLR1 36-38 have been associated with tumor occurrence and development." (PMID 34093861, 2021). "It is also noteworthy that the aberrant expression of FUT8 is commonly found in a variety of tumor cells." (PMID 34857735, 2021). "Inhibition of FUT8 reduces cell-surface expression of PD-1 by regulating the core fucosylation pathway and enhanced T-cell activation, leading to more efficient tumor eradication." (PMID 33976130, 2021). "FUTs are involved in tumour regulation, especially FUT8, which is considered to be directly related to tumours 9-10." (PMID 34093814, 2021). "The role of FUT8 in OS cell proliferation in vivo was also examined in the nude mice subcutaneous implantation tumor model." (PMID 34857735, 2021). "The protein FUT8 was investigated further in vivo, by comparing FUT8 expression in tumour sections of xenograft mice which were subjected to orchiectomy versus non-castrated mice (control group)." (PMID 34069262, 2021). "FUT8 expression level was also correlated with tumor histological grade (OR= 2.55, 95% CI: 1.10-5.95, p= 0.03)." (PMID 33323540, 2020). "We can observe that the results from the Huh7.5.1 and Lewis cells were similar, and thus, we can conclude that overexpression of FUT8 is highly related to drug resistance in Lewis tumor cells." (PMID 31022917, 2019). "In contrast to the tumor cells, the vast majority of adjacent mucosal cells lacks FUT8 staining, consistent with previous IHC studies for FUT8 in CRC, although some normal mucosal cells in the basal layer tended to exhibit weak/equivocal staining." (PMID 29975776, 2018). "It is worth noting that core fucosylation of alpha-fetoprotein (AFP-L3 fraction) due to the upregulation of FUT8 in HCC cells is a FDA-approved serum tumor marker for the specific diagnosis of HCC." (PMID 29975776, 2018). "Correspondingly, in human CRC specimens, FUT8 staining was primarily located within cytoplasm of tumor cells, which was occasionally accompanied by tumor cell membranous staining." (PMID 29975776, 2018). "Additional support for FUT8 involvement is found in reports that mRNA MiR-198 represses tumour growth and metastasis in CRC by targeting FUT834." (PMID 29872119, 2018). "The expression of fucosyltransferase 8, an enzyme responsible for core fucosylation encoded by FUT8, influences tumor biology and correlates with patient prognosis in several solid cancers." (PMID 29975776, 2018).
tumor (continued). "We also detected the expression of FUT8, β-catenin, N-cadherin, and Oct4 in mouse xenograft tumor tissues by immunohistochemistry." (PMID 28798691, 2017). "We detected decreased Fut8 protein expression in tumor tissue, which supported our findings in sera." (PMID 24732908, 2014). "In a subset of 24 paired samples (tumor tissue compared with non-tumor tissue from the same patient), we found a statistically significant enhance in Fut8 expression in poor differentiation as compared with well and moderate (P = 0.04)." (PMID 24927126, 2014). "Immunohistochemistry revealed that the Fut8 was strongly positively expressed at the luminal borders of non-tumor gastric cells, however it weakly positively expressed in tumor cells." (PMID 24732908, 2014). "Studies have shown that FUT8 can promote tumor cell proliferation, invasion and metastasis and is closely related to the occurrence and development of HCC." (PMID 23977005, 2013). "In this study, we measured the levels of FUT8 in > 1500 clinical samples across multiple patient cohorts and verify upregulation of FUT8 in high grade tumours and in patients with metastasis, and further show that the levels of blood borne FUT8 are also increased in patients with aggressive disease." (PMID 40387385, 2025). "In CRC tumor tissues, FUT8 was found to be enriched in CD8T cells and CD8Tex cells." (PMID 40729369, 2025). "Knockdown of FUT8 in tumor cells significantly abrogated in vitro proliferation." (PMID 38548747, 2024). "Beyond its eminent role in metastasis and immune evasion, FUT8 also influences other tumor behaviors, including proliferation, stemness, apoptosis, and tumorigenesis, although the degree of influence may vary across different types of tumors." (PMID 38256141, 2024). "Additionally, we also proved that circFUT8 functions as the tumor oncogene dependent on the parental coding protein FUT8." (PMID 37669906, 2023). "Our study demonstrated that circFUT8 could interact with both YTHDF2 and miR‐186‐5p to function as a tumor oncogene dependent on the parent protein of FUT8." (PMID 37669906, 2023). "In this study, we screened the MeRIP‐seq, YTHDF2‐RIP‐seq, and identified that the upregulated circFUT8 in LUAD tumor samples, derived from the exon 3 of FUT8, could be recognized by m6A reader protein YTHDF2." (PMID 37669906, 2023). "Interestingly, MET and EGFR molecules are substrate for FUT8 and the altered glycosylation increases their function with an overall gain of motility and proliferation for the tumor cells." (PMID 35682991, 2022). "FUT8 overexpression inhibited tumor growth, while FUT8 knockdown enhanced tumor growth." (PMID 34857735, 2021). "Given that core fucosylation of B7H3 mediated by FUT8 stabilizes its expression, we investigated whether blocking this modification impacts anti-tumor immunity." (PMID 33976130, 2021). "Together, these results support the hypothesis that FUT8 regulates OS tumor growth through cell apoptosis." (PMID 34857735, 2021). "FUT8 and core fucosylated glycoproteins are frequently upregulated in human tumours and may be used as markers for tumour diagnosis." (PMID 34093814, 2021). "Conceivably, increasing the expression of FUT8 or suppress the NF-κB2 signaling pathway in tumor cells of patients with OS may provide a new approach to attenuate the tumor burden of OS in the future." (PMID 34857735, 2021). "Thus, dysregulation of FUT8 would have effects on tumor development, and consequently on clinical prognosis of patients." (PMID 33323540, 2020).